PDCD2L (programmed cell death 2 like)
Description:
May function as a chaperone for ribosomal protein uS5; its function appears redundant to PDCD2.
Synonyms: MGC13096
Tractability: PROTAC: ubiquitination databases record sites on it.
Gene: Protein-coding gene on chromosome 19 (34,404,399 to 34,426,168, forward strand). Ensembl gene ENSG00000126249.
Subcellular location: Nucleus, nucleolus; Cytoplasm, cytosol
Subcellular location (Human Protein Atlas): Mitochondria
Gene Ontology:
Molecular function: protein binding
Biological process: apoptotic process
Cellular component: membrane; cytoplasm; cytosol; nucleolus
Genetic constraint (gnomAD): Loss-of-function variants: 32 observed, 31.29 expected, observed/expected ratio (o/e) 1.02, 90% interval 0.77 to 1.37. The upper end of that interval is the gene's LOEUF score, 1.37, which puts it in group 5 of 6, group 1 being the genes least tolerant of losing a copy. Missense variants: 401 observed, 383.67 expected, observed/expected ratio (o/e) 1.05, 90% interval 0.96 to 1.13. Synonymous variants: 175 observed, 150.81 expected, observed/expected ratio (o/e) 1.16, 90% interval 1.02 to 1.32.
Homologues: Orthologues: macaque PDCD2L (96% identical), chimpanzee PDCD2L (82% identical), dog PDCD2L (82% identical), pig PDCD2L (82% identical), guinea pig PDCD2L (77% identical), mouse Pdcd2l (71% identical), rat Pdcd2l (65% identical), tropical clawed frog pdcd2l (43% identical), zebrafish pdcd2l (41% identical), Drosophila melanogaster trus (31% identical). Paralogues in human: PDCD2 (26% identical), ZMYND12 (12% identical).
Diseases named in the same sentence as PDCD2L in open-access papers:
PDCD2L is named in the same sentence as 33 diseases in open-access papers, as found by Europe PMC text mining. Sharing a sentence is not in itself a finding about the gene and the disease. The quoted sentences say what the papers report.
colorectal cancer (2 papers, 2022 to 2024). A primary or metastatic malignant neoplasm that affects the colon or rectum. "Still, there have been few studies of PDCD2L in cancer, with only one study confirming that PDCD2L expression increases and promotes the proliferation of colorectal cancer cells." (PMID 39707202, 2024). "That knockdown of PDCD2L promotes apoptosis in colorectal cancer cells." (PMID 39707202, 2024). "Programmed Cell Death 2 Like (PDCD2L) is closely related to apoptosis and proliferation, but there are few studies on PDCD2L in cancer; only one study reported that PDCD2L is highly expressed in colorectal cancer and promotes cell proliferation and inhibits apoptosis in colorectal cancer." (PMID 39707202, 2024).
breast invasive carcinoma (1 paper, 2022). "PDCD2L expression was negatively associated with cancer associated fibroblast in breast invasive carcinoma (BRCA), lung squamous cell carcinoma (LUSC), sarcoma (SARC), stomach adenocarcinoma (STAD) and testicular germ cell tumors (TGCT)." (PMID 35216602, 2022).
Globozoospermia (1 paper, 2020). Any structural anomaly of the acrosome resulting in a round sperm head. "Whole exome sequencing performed on infertile men with globozoospermia identified a point mutation in the gene PDCD2L, as described in our previous work." (PMID 33055224, 2020). "In a previous study we identified candidate infertility-causing variants in PDCD2L in two brothers with globozoospermia." (PMID 33055224, 2020). "The variant we identified in the two brothers with globozoospermia was predicted to create a novel splice donor site, which was slightly weaker than the wildtype splice site nearby but nevertheless potentially disrupts splicing of PDCD2L." (PMID 33055224, 2020).
hepatocellular carcinoma (1 paper, 2024). A malignant tumor that arises from hepatocytes. "Meanwhile, we provide reliable evidence for the potential application of BTF3 and PDCD2L as diagnostic and prognostic biomarkers and therapeutic targets in hepatocellular carcinoma." (PMID 39707202, 2024). "We also demonstrated that PDCD2L is highly expressed in hepatocellular carcinoma and regulates the proliferation and apoptosis of hepatocellular carcinoma cells to promote the progression of hepatocellular carcinoma." (PMID 39707202, 2024). "Meanwhile, correlation analysis revealed that the expression of PDCD2L was highly correlated with that of BTF3 in 29 pairs of hepatocellular carcinoma tissues, which indirectly indicated the regulatory relationship between BTF3 and PDCD2L." (PMID 39707202, 2024). "Our work shows that BTF3 can directly act on the promoter of PDCD2L to promote the transcription of PDCD2L and exert oncogenic effects in hepatocellular carcinoma." (PMID 39707202, 2024). "To ascertain the effect of PDCD2L on the proliferation of hepatocellular carcinoma cells, we performed CCK8, EDU, and clone formation assays, which showed that knockdown of PDCD2L significantly inhibited the proliferation of hepatocellular carcinoma cells." (PMID 39707202, 2024). "In the current study, we investigated the biological role of BTF3 in hepatocellular carcinoma and confirmed that PDCD2L is a downstream target of BTF3 as a transcription factor." (PMID 39707202, 2024). "We verified the changes of PDCD2L expression in hepatocellular carcinoma cell lines after transfection by q-rtPCR." (PMID 39707202, 2024). "To investigate the role of PDCD2L in hepatocellular carcinoma, we first verified that the mRNA and protein expression of PDCD2L in hepatocellular carcinoma tissues was significantly higher than that in paracellular carcinoma tissues." (PMID 39707202, 2024). "In this study, we identified a novel role of BTF3 in hepatocellular carcinoma through transcriptional up-regulation of PDCD2L involved in the proliferation and apoptosis of hepatocellular carcinoma cells." (PMID 39707202, 2024). "To confirm the relationship between BTF3 and PDCD2L, we first observed the expression level of PDCD2L in hepatocellular carcinoma cells knocking down and overexpressing BTF3, and the results showed that the expression of PDCD2L was in the same trend of change as that of BTF3." (PMID 39707202, 2024). "Meanwhile, knockdown of PDCD2L promoted apoptosis in hepatocellular carcinoma cells as detected by flow cytometry, and this could be rescued by BTF3 overexpression." (PMID 39707202, 2024). "Subsequently, we knocked down the overexpression of PDCD2L in hepatocellular carcinoma cell lines." (PMID 39707202, 2024). "We also investigated the natural role of PDCD2L in hepatocellular carcinoma and its mechanism." (PMID 39707202, 2024). "The role of PDCD2L in hepatocellular carcinoma needs to be further studied." (PMID 39707202, 2024). "At the same time, overexpression of PDCD2L promoted the activity of hepatocellular carcinoma cells while knockdown of BTF3 could partially reverse this trend." (PMID 39707202, 2024). "Also, it confirmed the oncogenic role of PDCD2L in hepatocellular carcinoma for the first time." (PMID 39707202, 2024). "To clarify the mechanism of BTF3 as a transcription factor in hepatocellular carcinoma, we then utilized the chip-seq data and transcriptome data to identify potential targets of BTF3 and finally focused on the PDCD2L molecule." (PMID 39707202, 2024).
liver cancer (1 paper, 2024). An epithelial or non-epithelial malignant neoplasm that arises from the liver. "The results showed that knockdown of PDCD2L significantly inhibited the proliferation of liver cancer cells." (PMID 39707202, 2024).
type 2 diabetes (1 paper, 2016). "Our results suggested that FoxO1 may exert its activity partially through the regulation of Pdcd2l in palmitate-induced β cell apoptosis and could help to clarify the molecular mechanisms of β cell failure in type 2 diabetes." (PMID 27861641, 2016).
cancer (7 papers, 2022 to 2025). A tumor composed of atypical neoplastic, often pleomorphic cells that invade other tissues. "Our study found that PDCD2L was aberrantly expressed in multiple types of human cancers, and associated with clinical stage and molecular subtype." (PMID 35216602, 2022). "In conclusion, our study first provides a comprehensive analysis of PDCD2L in pan-cancer and found that PDCD2L expression was high in various cancers and negatively associated with CAF." (PMID 35216602, 2022). "PDCD2L might play an oncogene role in various cancers, the underlining mechanism of PDCD2L regulating CAF needs further study." (PMID 35216602, 2022). "For example, vertebrate PDCD2L has been linked to apoptosis and has been found to be over expressed in many cancer cell lines, which could be consistent with Trus being a component of several different molecular machines, each affecting a specific cellular process." (PMID 39484569, 2024). "KIT overexpression has been linked to a poor prognosis in cases with monosomy 3, and aberrant expression of PDCD2L (programmed cell death 2 like) has been observed across various types of cancers, including UM." (PMID 38920653, 2024). "To explore the co-expression network and enrichment pathways of PDCD2L in pan-cancer, firstly, we predicted the binding proteins of PDCD2L by STRING website, which were validated by experiment." (PMID 35216602, 2022). "Multiple bioinformatic methods, in vitro function experiments and validation were performed to clarify the oncogenic role of PDCD2L in human cancers." (PMID 35216602, 2022). "To further investigate the underlying mechanism of the correlation between PDCD2L expression and CAF, we analyzed the expression markers of CAF in pan-cancer." (PMID 35216602, 2022). "Our result showed that positive PDCD2L signal was located in cytoplasm of carcinoma cell in our CRC samples." (PMID 35216602, 2022). "As shown by the cancer dependency map, most cancer cell lines survive a deletion of PDCD2L." (PMID 37238722, 2023). "Moreover, single cell sequencing data was applied to investigate relevant cancer cell status of PDCD2L." (PMID 35216602, 2022). "Our above results suggested that PDCD2L might play an oncogene role in pan-cancer and could be used as a prognostic marker." (PMID 35216602, 2022). "Our study shows that the oncogenic role of PDCD2L in various cancers and PDCD2L could be served as a biomarker of CRC." (PMID 35216602, 2022). "PDCD2L is evolutionarily conserved in development.Since the role of PDCD2L in cancer progression remains unclear, we systematically analyzed the expression and prognosis value of PDCD2L in pan-cancer." (PMID 35216602, 2022). "Firstly, we analyzed PDCD2L expression in pan-cancer through ONCOMINE website." (PMID 35216602, 2022). "The result suggests PDCD2L might be as oncogene in these cancers." (PMID 35216602, 2022). "Furthermore, we validated PDCD2L expression in pan-cancer by TIMER2.0." (PMID 35216602, 2022). "To elucidate the role of PDCD2L in TME, we analyzed the correlation between PDCD2L expression and TME components in pan-cancer by TIMER 2.0 website." (PMID 35216602, 2022). "However, the role of PDCD2L is still unknown in various cancers." (PMID 35216602, 2022). "Our study revealed that PDCD2L was highly expressed in various cancers compared with the corresponding non-tumor tissues." (PMID 35216602, 2022).
tumor (2 papers, 2022 to 2024). "By collecting 10 pairs of fresh CRC tissues and corresponding adjacent tissues for qPCR and WB detection, we found that the transcription level and protein level of PDCD2L in CRC tissues were significantly higher than those in non-tumor adjacent colorectal mucosa tissues." (PMID 35216602, 2022). "And PDCD2L was highly expressed in CRC tissues compared with non-tumor colorectal mucosa tissues." (PMID 35216602, 2022). "Furthermore, we also detected PDCD2L expression in our CRC samples and found that the expression of PDCD2L is significantly higher in CRC tissues than that in corresponding non-tumor colorectal mucosa tissues." (PMID 35216602, 2022). "Our validation experiment found that PDCD2L expression was significantly higher in CRC samples than that in corresponding non-tumor tissues, which suggests that PDCD2L could be served as a biomarker of CRC." (PMID 35216602, 2022). "Firstly, we performed IHC to detect PDCD2L expression in 126 pairs of paraffin-embedded tissues of CRC and non-tumor adjacent colorectal mucosa tissues." (PMID 35216602, 2022).
PDCD2L also shares sentences with these, for which no sentence is quoted: acute myeloid leukemia (1 paper); adrenocortical carcinoma (1); bladder urothelial carcinoma (1); breast carcinoma (1); cervical squamous cell carcinoma (1); colon adenocarcinoma (1); endocervical adenocarcinoma (1); Esophageal carcinoma (1); head and neck squamous cell carcinoma (1); Infertility (1); kidney chromophobe (1); lung adenocarcinoma (1); lung squamous cell carcinoma (1); mesothelioma (1); ovarian carcinoma (1); pancreas cancer (1); prostate adenocarcinoma (1); prostatic cancer (1); rectum adenocarcinoma (1); renal cell carcinoma (1); sarcoma (1); testicular germ cell tumor (1); Thyroid carcinoma (1); uterine corpus endometrial carcinoma (1); uveal melanoma (1).